TNF (tumor necrosis factor)
Diseases named in the same sentence as TNF in open-access papers (continued):
Sharing a sentence is not in itself a finding about the gene and the disease.
Stroke (continued). "Generally, elevated levels of circulating proinflammatory cytokines, including tumour necrosis factor-alpha (TNF-α), IL-6, and interleukin 1β (IL-1β), are related to a poor prognosis in stroke sufferers." (PMID 34335867, 2021). "The enhanced serum levels of TNF and IL-6 in stroke patients were tested on days 1, 3, and 7 after stroke when compared to the control group." (PMID 33953667, 2021). "Results showed a noticeable increase in hypoxia-inducible factor 1 and IL-10 levels in the DMOG group with a decline in iNOS, TNF-α, and NF-kB levels, implying the anti-inflammatory role of hypoxia-inducible factor 1 activator following stroke." (PMID 34205911, 2021). "In the present work, we further showed that treatment with QSYQ (600 mg/kg) significantly reduced the mRNA levels of TNF-α and IL-6 in brain tissues of stroke rats after ischemia and reperfusion." (PMID 33953667, 2021). "Initiation of inflammation after stroke worsens the functional prognosis, while treatments that target inflammatory cytokines, such as TNFα and IL-1, have been shown to be effective in restoring neurological outcomes after stroke." (PMID 34327147, 2021). "For example, a positive correlation was found between the TNF expression level and phagocytic activity in stroke-lesioned rodent brain." (PMID 35082781, 2021). "We found that protein expressions of intestinal TNF-α and apoptosis-related proteins caspase-3 and cleaved caspase-3 significantly increased after stroke in mice." (PMID 33642941, 2021). "To extend our previous stroke study centered on TNF-α, here we determined the effects of a TNF-α receptor antagonist, R-7050, on the poststroke inflammatory and metabolic changes in a rat model of permanent stroke." (PMID 34073455, 2021). "Studies suggested that depressive symptoms are positively associated with inflammatory factors (i.e., C-reactive protein, IL-6, and Tumor necrosis factor alpha), which are related to stroke." (PMID 34706692, 2021). "Tumor necrosis factor (TNF) and interleukin-1 receptor antagonist (IL-1Ra) are key players in stroke, a disease in which cell-based therapies have shown great potential." (PMID 33924148, 2021). "In contrast to the brain, stroke markedly increased expression of inflammatory-related factors, including IL-17a, TNFα, and TLR4, in the gut; however, IL-1β and MCP-1 levels were not increased as in the brain." (PMID 34327147, 2021). "The inflammatory mediator tumor necrosis factor alpha (TNFα) is one of the prominent cytokines known to be upregulated after stroke and is related to BBB break-down, as observed by us and many others." (PMID 34571963, 2021). "In experimental stroke model of rodents, the increased expression levels of TNF-α mRNA and protein were observed in ischemic brain tissues." (PMID 33953667, 2021). "Overall, our findings highlight a feasible way to combat stroke disease based on an anti-TNF therapy that involves anti-inflammatory and metabolic mechanisms." (PMID 34073455, 2021). "There is evidence that TNF-a and IL-1B levels in the brain increase many-fold (up to 40 or 60 times) during the first 24 h after inducing stroke." (PMID 34600570, 2021). "Among 24 individuals with a history of one or more strokes, in 3622 patient months prior to anti-TNF therapy, there were 76 strokes reported." (PMID 35095905, 2021). "The only patient missing anti-TNF initiation, who had the lowest level of TNF-α, unfortunately had a stroke 6 months after onset." (PMID 33757531, 2021). "As early as 3 h after ischemic stroke, TNFα mRNA levels are increased and protein expression follows to rise at around 6 h post stroke." (PMID 34571963, 2021). "In the context of regulation of TJs proteins under different conditions, TNF-α has been shown to stimulate stroke-like conditions in the BBB, which was mimicked in vitro by using Transwell assay." (PMID 34294165, 2021).
Stroke (continued). "Caspase-1 activity, IL-1β, TNF-α, and NLRP3 have been demonstrated to be associated with modulation of apoptosis after stroke, causing activation of caspase-dependent pathways of cell death." (PMID 34257822, 2021). "KEGG analysis of the candidate targets identified that luteolin provides therapeutic effects on stroke through TNF signaling and other pathways." (PMID 34898370, 2021). "In postmortem studies, TNF-α positive cells are observed in all brains of patients with severe ischemic stroke 3 days after stroke and are present up to 15 months after indecent." (PMID 34433866, 2021). "Salivary TNF-α, IL-6, and IL-10 as well as TNF-α/IL-10 and IL-6/IL-10 ratio significantly distinguish stroke patients from controls with high sensitivity and specificity." (PMID 34433866, 2021). "The study was the first of its kind showing inhibition of TNF alpha secretion from stroke-activated microglia/macrophages after naloxone." (PMID 34206997, 2021). "Salivary TNF-α differentiates stroke patients from controls with high sensitivity and specificity and correlates with cognitive dysfunction in the ACE III scale and severity of functional impairment in the BBS and ADL scale." (PMID 34433866, 2021). "Microglia, as the resident immune cells in CNS, can be activated after stroke and initiate neuroinflammation by producing cytotoxic and inflammatory factors including IL-1β and TNF-α to thereby exacerbate brain damage." (PMID 34898370, 2021). "mRNA expression of TNFα and IL-1β in ischemic brain tissue on day 3 after stroke onset was also decreased in mice treated with anti-DJ-1 antibody." (PMID 34014921, 2021). "Based on the 95 crossover genes identified, PPI network analysis uncovered six core genes including MMP9, MAPK3, PTGS2, JUN, IL1B and TNF likely linking the activity of luteolin to effective stroke control." (PMID 34898370, 2021). "During the acute period after stroke, microglia secrete pro-inflammatory cytokines IL-6, TNF-α, and IL-1β, which can induce secondary cytotoxicity." (PMID 33479185, 2021). "To understand the effect of HDAC1 in pathologic mechanism of stroke, we examined the levels of ROS, LDH, IL-1β, and TNF-α on day 3 after stroke." (PMID 34381129, 2021). "The study has indicated that TNF-α, IL-1β, and IL-6 secreted by activated microglia involve in neuronal cell apoptosis at stroke onset." (PMID 34257822, 2021). "In another acute CNS injury study, it has been shown that the peripheral neutralisation of TNF after stroke gives rise to an increase in hepatic TNF expression, yet the number of granulocytes in the infarct was reduced." (PMID 33407641, 2021). "Our results suggest that HIF-1α improves stroke outcomes by enhancing IL-10 levels, and curtailing iNOS, TNF-α and NF-kB levels." (PMID 34205911, 2021). "The levels of TNFα in blood circulation and cerebrospinal fluid rise rapidly following a stroke, and stroke lesion size has a positive correlation with TNFα levels." (PMID 33643574, 2021). "Data has shown that TNFα can actively protect neurons and that mice deficient in TNFp55 receptors show increased stroke volume, while overexpression of TNF-α is detrimental to stroke outcome." (PMID 34072307, 2021). "Salivary TNF-α differentiates (with high sensitivity and specificity) stroke patients with normal cognitive function from patients with mild to moderate cognitive impairment." (PMID 34433866, 2021). "We prevented “A1” neurotoxic astrocyte formation after stroke withtriple knockout (TNF-, Il-1a-, and C1q-) mice, and compared their neuroinflammatory responseand stroke size to wildtype mice." (PMID 34612709, 2021). "The levels of inflammatory cytokines IL-1β, TNFα, and IL-6 in the blood of stroke patients and MCAO/R mice are increased." (PMID 34422821, 2021).
Stroke (continued). "As plasma IL-6 levels obtained within the first week post-stroke have been shown to correlate with brain infarct volume, stroke severity, and long-term outcome, we also investigated plasma IL-6 levels and their possible correlation with TNF, TNFR1, and TNFR2." (PMID 33918875, 2021). "IL-1β and TNFα levels in serum and plasma have been investigated and some studies reported an increase shortly after the stroke, whereas others did not." (PMID 34966269, 2021). "Cytokine-based multimarker score composed of ex vivo released IL-12, IL-10, TNFα, and plasma IL-6 adds prognostic value to clinical model for predicting stroke outcome." (PMID 31906994, 2020). "Overexpression of miR-126 in ADSC-derived exosomes further enhanced not only neurogenesis and angiogenesis, but also suppression of microglial activation and TNF-α and IL-1β production after stroke." (PMID 32962207, 2020). "In an exploratory analysis, the numbers of reactive CD3+ lymphocytes producing TNF-α was significantly higher in the subgroup of patients with poor outcome at 90 days after stroke." (PMID 32719588, 2020). "We showed previously that TNF and IL-1β and IL-1α, IL-1β, IL-1Ra are produced by subsets of microglia in experimental stroke." (PMID 32503645, 2020). "Studies have reported a positive association between tumor necrosis factor alpha (TNF-α) and IL-1β with ischemic stroke risk or future stroke recurrence." (PMID 33153204, 2020). "HDLs from stroke patients, independently of their outcome, significantly limited TNFα-induced expression of VCAM1 (increase) and CLDN1 (decrease) gene expression." (PMID 32708891, 2020). "A rising quantity of TNF-α can be seen in patients affected by a stroke just 6–12 h following the appearance of the symptomatology." (PMID 32899616, 2020). "Stroke mice receiving the hypothermic treatment showed a lower neurological severity score and a decreased expression of inflammatory factors including TNF-α, MMP-9, and IL-1β." (PMID 33381263, 2020). "In stroke, the inflammatory factors secreted by activated microglia (M1), such as TNF-α, IL-1β, and IL-6, are significantly elevated." (PMID 32733433, 2020). "Experimental stroke studies have shown decreases in markers of inflammation, such as tumor necrosis factor-alpha and CD40+ microglia in HBOT-treated animals." (PMID 32899709, 2020). "ADAM17, an inhibitor of MMP, is also considered as a potential stroke therapy because it diminishes TNFα production." (PMID 33153204, 2020). "The mRNA levels of proinflammatory factors, including tumor necrosis factor-α (TNF-α), interleukin-1β (IL-1β) and interleukin-6 (IL-6) were significantly increased 1 to 7 days after stroke." (PMID 32010477, 2020). "It has been described that during the first hours after stroke, pro-inflammatory cytokines are up-regulated (IL-6, IL-1, TNFα, IL-8, MCP-1, etc)." (PMID 32111174, 2020). "Proinflammatory microglia prevail in the acute phase following stroke, along with enhanced expression of tumor necrosis factor‐alpha (TNF‐α), interleukin (IL)‐1β, IL‐12, and inducible nitric oxide synthase (iNOS)." (PMID 32757264, 2020). "One month after LPS treatment, the priming of LPS induced significantly higher IL-1β, IL-6, and TNF-α production 24 h after the subsequent stroke, and infarct size was also exacerbated by the LPS priming." (PMID 33013828, 2020). "The present study demonstrated that the Dectin-1, Syk, p-Syk, TNF-α, and iNOS expression levels were significantly increased in ischemic brain tissue after a stroke." (PMID 31926564, 2020). "LPS stimulation significantly increased the levels of pro-inflammatory markers, including IL-6, iNOS, and TNFα, which are reported to exacerbate brain damage during stroke." (PMID 32489699, 2020). "Polyclonal stimulation with PMA-Ionomycin also showed higher percentages of CD3+ lymphocytes producing IFN-γ, TNF-α, or IL-10 at admission compared to day 5 after stroke." (PMID 32719588, 2020).
Stroke (continued). "The serum levels of sTREM-1, TNFα, IL-6, and S100B were correlated with the stroke volume and NIHSS, after acute ischemic stroke." (PMID 33375339, 2020). "The inflammatory cytokines interleukin (IL)-1 and tumor necrosis factor (TNF) are pivotal in regulating immune responses following ischemic stroke and are potential targets in stroke therapy." (PMID 32503645, 2020). "For example, tumor necrosis factor (TNF) is one of the most widely studied cytokines in stroke, and preclinical data indicates both neurotoxic and neuroprotective effects of TNF." (PMID 33192321, 2020). "To verify the anti-inflammatory function of Gen after reproductively senescent stroke, we evaluated inflammatory factors, including TNF-α, IL-1β, IL-18, and IL-6 in ischemic penumbra area 24 h after reperfusion." (PMID 32625078, 2020). "It is known that there is a positive correlation between inflammatory cytokines (TNF-α, IL-1β, IL-6, etc.)and microglial activity after stroke." (PMID 32922507, 2020). "The iNOS‐expressing microglia/macrophages secrete pro‐inflammatory cytokines such as interleukin‐1 beta (IL‐1β) and tumour necrosis factor alpha (TNF‐α), which subsequently exacerbate brain injury in stroke." (PMID 32713053, 2020). "Despite these limitations, we were able to identify increased production of both proinflammatory TNF-α, and anti-inflammatory IL-10 in response to neural peptides in lymphocytes of stroke patients at admission vs. day 5 post-stroke." (PMID 32719588, 2020). "The results demonstrated that proinflammatory cytokines TNF-α (p < 0.05), IL-6 (p < 0.001), IL-1β (p < 0.01), IL-17 (p < 0.01), and IL-18 (p < 0.01) were increased in wild-type mice subjected to stroke." (PMID 32450881, 2020). "In stroke mice, the hypothermia treatment markedly reduced the mRNA level of pro-inflammatory factors TNF-α and IL-6 at 1 to 3 days after stroke and IL-6 l at 1 and 7 days after stroke, respectively." (PMID 32010477, 2020). "Relevant reduction of TNFα and IL-6 expression, microglia and vascular activation have been demonstrated by the authors in a mouse model of stroke." (PMID 32974295, 2020). "After building stroke model, the mRNA levels of TNF-α and iNOS of penumbra of stroke and stroke+PBS groups were markedly upregulated (∗∗∗P < 0.001)." (PMID 32908485, 2020). "Npas4 knock-out mice also exhibited higher levels of the pro-inflammatory cytokines IL-6 and TNF-α post-stroke, and stroke-induced upregulation of Npas4 was found in brain regions linked to emotion and cognition." (PMID 33335473, 2020). "There is also well-documented evidence indicating that monitoring of TNFα and IL-1β levels can provide some valuable information allowing for diagnosis of stroke in patients with accompanying metabolic disorders and those without such complications." (PMID 31701356, 2020). "In the literature, TNF-α increases the risk of stroke in SCA patients, and SCA patients with higher levels of TNF-α had more frequent leg ulcers, acute chest syndrome, femoral necrosis, and recurrent infection." (PMID 33424841, 2020). "Pathological microglial activation is considered a pro-inflammatory source of neuronal damage after stroke, which initiates tumor necrosis factor (TNF)-α, interleukin (IL)-1β, IL-6, IL-12, and nitric oxide (NO) cascade in the brain." (PMID 33269103, 2020). "In conclusion, the decreased release of some pro-inflammatory cytokines (IP-10, TNFα, IL-1β, and IL-12p70) and increased release of IL-10 and IL-8 after ex vivo blood stimulation with LPS are related to poor outcome after stroke." (PMID 31906994, 2020). "Growing evidence suggests that TNF-α has a crucial function in the neuroimmunological development of stroke and has both a neurotoxic and a neuroprotective result in the ischemic brain." (PMID 32899616, 2020). "In particular, the group of strokes classified as CEI presented relevantly elevated plasma concentrations TNF-α, IL-6, and IL-1 in comparison with the other strokes." (PMID 32899616, 2020).
Stroke (continued). "In our experimental stroke model, we previously demonstrated that microglial-derived TNF is protective after focal cerebral ischemia, that Tnf−/− mice displayed increased lesion size but that ablation of solTNF reduceed lesion size." (PMID 33153044, 2020). "We observed significantly higher levels of proinflammatory cytokines IL-1β, IL-6, and TNF-α in plasma of stroke mice and the BR therapy decreased the levels of these cytokines in plasma." (PMID 32843630, 2020). "We found that the serum levels of sTREM-1, TNFα, IL-6, and S100B were correlated with the severity of stroke, as evaluated by TOAST and NIHSS after acute ischemic stroke." (PMID 33375339, 2020). "Syk inhibitor (PIC) treatment significantly attenuated p-Syk, TNF-α, and iNOS expression in the ischemic brain tissue after a stroke and in the OGD/R model." (PMID 31926564, 2020). "We therefore compared parallel tissue sections from two stroke cases stained for IL-1α, IL-1β, IL-1Ra, TNF, TNFR1, and TNFR2." (PMID 32503645, 2020). "PRNCs were subject to HBOT before exposure to tumor necrosis factor-alpha (TNF-alpha) or lipopolysaccharide (LPS) injury to induce stroke-like cell death." (PMID 32899709, 2020). "Losartan reduced MCP-1 and TNF-α from stroke-Mo and reduced IL-8 from cocultures of stroke-Mo and MSCs." (PMID 32802081, 2020). "TNF-a synthesis in neurons has already been reported in some pathological situations, including spinal cord injury, stroke, and sciatic nerve injury." (PMID 32087723, 2020). "It is known that TNF-α, Il-1, and Il-6 increase in amount, even 40–60 times, within 24 h after a stroke." (PMID 33076354, 2020). "In the gut, IL-6 and TNF-α gene expression levels were significantly higher at 6-h and 24-h post-stroke in Ag mice compared to age-matched controls." (PMID 32429999, 2020). "IL-6 and TNF-α are pro-inflammatory factors, the elevated concentrations of which are observed, inter alia, during stroke." (PMID 33187206, 2020). "Therapeutic hypothermia (TH) inhibited the M1 polarization of microglia and reduced the expression of inflammatory factors such as TNF-α, IL-1β, and iNOS in stroke mouse model." (PMID 33381263, 2020). "For example, high level of TNF-α released from the microglia M1 phenotype activation was disadvantaged in brain tissue and neuron recovery after stroke, while the microglia M2 factors exerted a neuroprotective role in various stages of acute ischemia stroke." (PMID 32908485, 2020). "The serum levels of catalase activity and malondialdehyde (MDA), and plasma tumor necrosis factor (TNF)-α levels were significantly increased in post-stroke patients compared with non-stroke controls." (PMID 33126675, 2020). "Cross sections of colon from naïve older mice were treated with recombinant TNF‐α for 1 hr in an ex‐vivo setting to mimic the induction of stroke‐induced pro‐inflammatory responses, and changes in gene expression of various tight junctions assessed." (PMID 31199577, 2019). "A common proinflammatory cytokine is TNF-α, which is involved in every phase of the stroke rehabilitation process." (PMID 31031649, 2019). "Clinically, elevated caspase-3/7 activity was reported in both acute and late phases of stroke patients, and acute caspase-3/7 activation correlated with TNF-α levels, which is an important mediator for IS progression." (PMID 31819117, 2019). "In the early stages of stroke, TNF-α promotes BBB breakdown, leukocyte infiltration, and brain oedema, while further along the timeline, it mediates neuronal and microvasculature repair." (PMID 31281252, 2019). "The earlier acute pro‐inflammatory response appears specific to the colon as circulating serum levels of TNF‐α and IL‐10 remain unchanged at both the 5‐ and 24‐hr time point following stroke." (PMID 31199577, 2019). "The levels of pro-inflammatory cytokines (e.g., IL-6, IL-1β, and TNF-α) were all induced by stroke in control mice." (PMID 31771656, 2019).